ENSG00000212224
Synonyms: LOC124900463
Gene: Small nucleolar RNA gene on chromosome 20 (41,712,479 to 41,712,600, reverse strand). Ensembl gene ENSG00000212224.
Gene Ontology:
Biological process: RNA processing
Cellular component: nucleolus
Homologues: Paralogues in human: SNORA26 (87% identical).